CEACAM1 (CEA cell adhesion molecule 1)
Diseases named in the same sentence as CEACAM1 in open-access papers (continued):
Sharing a sentence is not in itself a finding about the gene and the disease.
tumor (continued). "We next investigated the possibility that CEACAM1 on T cells could be up-regulated by PD-1 blockade upon TCR-mediated stimulation within the tumor microenvironment." (PMID 30349641, 2018). "Depending on the origin of the tumor, CEACAM1 might differently affect the tumorigenic process by acting as a tumor suppressor gene or as a metastatic driver." (PMID 30050594, 2018). "Furthermore, CEACAM1 is an adhesion molecule that is regarded as a tumor suppressor and was found to regulate tumor growth and apoptosis in many types of cancer including BC." (PMID 29930758, 2018). "Additionally, the present results demonstrated low expression of CEACAM1 on CD8+ tumor infiltrating T cells across three different tumor models." (PMID 30349641, 2018). "By secreting cytokines, chemokines or growth factors, as well as up-regulating specific surface receptors, e.g., PD-L1, CTLA-4, carcinoembryonic antigen-related cell adhesion molecule 1 (CEACAM1), and others, tumor cells become competent in dampening and finally escaping the immune system." (PMID 30577587, 2018). "Conversely, CEACAM1 downregulation stimulated MRO cell tumor growth with reduced invasiveness." (PMID 30406153, 2018). "Moreover, the expression levels of ATF3 in CRC correlated with the expression of its target genes, such as CEACAM1, DUSP14, HDC, HLF and ULBP2, which are required for tumor cell invasion and proliferation and are robustly linked to poor prognosis in CRC." (PMID 28402947, 2017). "Carcinoembryonic antigen related cell adhesion molecule 1 (CEACAM1) is a trans-membrane multifunctional cell adhesion molecule associated with tumor cell proliferation, apoptosis, angiogenesis, invasion, and migration during tumor development." (PMID 27074014, 2016). "Moreover, CEACAM1 induces Sox-2 overexpression, which in turn induces β-catenin expression, a mechanism involved in acquiring tumor aggressiveness." (PMID 27642217, 2016). "Serum CEACAM1 readily followed tumor volumes and dropped dramatically two days after excision." (PMID 26688824, 2015). "In cases where the excision was complete, serum CEACAM1 gradually vanished from the circulation, whereas in cases where tumor cells remained and tumor recurred, it reincreased in parallel to the elevation in tumor mass." (PMID 26688824, 2015). "We next tested whether serum CEACAM1 levels follow the clinical scenarios of tumor excision and recurrence." (PMID 26688824, 2015). "Our results revealed that overexpression of CEACAM1 on tumor cells may promote neutrophils infiltration." (PMID 24587171, 2014). "These researches implied that CEACAM1 overexpression in TSCC may also promote tumor progression and so as to be correlated with poor clinical outcomes." (PMID 24587171, 2014). "Among the members of the CEA family, the CEA-related cell adhesion molecule 1 (CEACAM1), also known as CD66a, is expressed on several types of cell including human granulocytes and lymphocytes, endothelia, epithelia, extravillous trophoblasts and some tumour cells." (PMID 24599281, 2014). "Astrocyte elevated gene-1 [AEG-1; also known as Metadherin (MTDH) and Lysine-rich CEACAM1 co-isolated (LYRIC)] has emerged in recent years as a potentially crucial mediator of tumor malignancy, and a key converging point of a complex network of oncogenic signaling pathways." (PMID 25009642, 2014). "Indeed, CEACAM1 is a tumor suppressor gene that is down-regulated in most tumor cells such as colon, breast and prostrate cancer." (PMID 24650050, 2014). "Given its previously reported function in regulating tumor cell differentiation and the immune system, future studies investigating the role of CEACAM1 in pathologic bone conditions, such as tumor-induced osteolysis and inflammation-induced bone loss, will be of crucial importance." (PMID 25490771, 2014). "The overexpressed CEACAM1 may attract more neutrophils to tumor sites through up-regulating IL-8 and CXCL-6 expression." (PMID 24587171, 2014).
tumor (continued). "This indicated that CEACAM1 may attract more neutrophils to the tumor sites through upregulating neutrophil chemokines’ expression." (PMID 24587171, 2014). "When we investigated whether invasive CEACAM1 positive mouse cells on the tumor front might be responsible for the AS we observed for human CEACAM1 MDA-MB-468 cells, we observed little staining with antibody CC1, which recognizes mouse CEACAM1 exclusively." (PMID 24650050, 2014). "However, the research of the effect of CEACAM1 from tumor cells on inflammatory cells remains limited." (PMID 24587171, 2014). "Reports indicated that increased CEACAM1 is strongly associated with NSCLC and correlated with metastasis and progression, and its expression could be determined in tumour tissue by immunohistochemistry." (PMID 23885995, 2013). "CEACAM1 also functions as an epithelial tumor suppressor and as an angiogenic growth factor." (PMID 23613893, 2013). "CEACAM1 mediates various key signal transduction pathways in tumour progression." (PMID 23885995, 2013). "Additionally, the inhibition of tumour growth upon CEACAM1 re-expression in tumour cells was reported to led to the original definition of CEACAM1 as a tumour suppressor." (PMID 23885995, 2013). "Previous reports demonstrated that soluble CEACAM1 could be produced by tumour cells and the endothelial cells of angiogenic microvessels." (PMID 23885995, 2013). "However, more recent reports showed that tumor derived MVs are able to increase stimulated T-cell proliferation and also CEACAM1 can act as intensifying co-receptor of the T-cell receptor." (PMID 24040308, 2013). "Furthermore we analyzed the signaling properties of CEACAM1 in MVs and the function of tumor derived CEACAM positive MVs on T-lymphocytes." (PMID 24040308, 2013). "Thus, blocking of CEACAM1 is expected to enhance the immune response only within tumor sites and only in the context of antigen-restricted recognition." (PMID 22778766, 2012). "Tumor expression of Ceacam1 may regulate tumor angiogenesis and invasion, and the expression of both Ceacam1 and CEA by tumors may inhibit the functions of tumor infiltrating lymphocytes." (PMID 21760897, 2011). "Identification of CEACAM1 as a MHC-I-independent NK inhibitory receptors provided new insights toward understanding tumor immune evasion mechanisms, since the binding partners of CEACAM1—CEACAM1 itself and CEACAM5—are widely present in various types of cancers." (PMID 21731662, 2011). "Ceacam1 also regulates angiogenesis, energy homeostasis, and tumor biology." (PMID 21760897, 2011). "This possibly links CEACAM1 to the Wnt signalling pathway which could explain CEACAM1's role in differentiation and tumour formation upon downregulation." (PMID 20132533, 2010). "Furthermore, we analyzed splicing profiles of two additional genes: GLI1 oncogene and CEACAM1 tumor suppressor whose disturbed splicing is known to contribute to tumor progression." (PMID 21082031, 2010). "The scFv MA39 antibody was affinity-maturated by in vitro mutagenesis and the new scFv clone, E8, was isolated, typed for CEA family member recognition and its CEACAM1, 3 and 5 shared epitope characterized for expression in a large panel of human normal and tumor tissues and cells." (PMID 16504122, 2006). "The epithelial origin of the tumor cells was proven by morphological criteria including the presence of mucin within the cells and the expression of the cell adhesion molecules EpCAM and CEACAM1." (PMID 16536871, 2006). "The epithelial origin of the tumor cells was proven by morphological criteria including the presence of mucin within the cells and the expression analysis of protein commonly expressed in epithelial cells (EpCAM, E-cadherin, CEACAM1)." (PMID 16536871, 2006). "This indirectly suggests CEACAM1 expression may foster Th2 responses in the tumor." (PMID 38956268, 2024). "It remains unclear if CEACAM1-LΔ461 is tumor-promoting or tumor-suppressive." (PMID 36741860, 2023).
tumor (continued). "Hence, CEACAM1 blockade enhances the ability of the immune system to kill tumour cells." (PMID 36928507, 2023). "Currently, whether CEACAM1 promotes or inhibits tumor progression has been controversial." (PMID 36712923, 2023). "Therefore, CEACAM1 may act as a tumor suppressor for ccRCC, and its reduced expression in tumor tissues contributes to tumor progression." (PMID 36712923, 2023). "Therefore, the concept of CEACAM1 as a tumor suppressor needs to be revised." (PMID 38077351, 2023). "The ambiguous role of CEACAM1 in human malignancies, reported both as a tumor suppressor or as a tumor progression, angiogenesis, and immune evasion factor, depending on malignancies, could be explained by variations in IDE expression or catalytic activity in different pathological settings." (PMID 35406791, 2022). "It suggests that the roles of CEACAM1 in tumor and normal tissues may be different." (PMID 35812245, 2022). "In addition, F. nucleatum bound and activated the cell inhibitory receptor CEACAM1 on CEACAM1 + TILs and CEACAM1 + tumor cells, indicating its potential importance in modulating antitumor immunity, which helped the tumor evade immune cell attack through an additive mechanism." (PMID 35222330, 2022). "While elegant studies in T lymphocytes have shown that CEACAM-1 engagement by the fusobacterial adhesin CbpF inhibits the T cell response and antitumor immunity, the consequences elicited by the same interaction on the tumor cell side remain largely uninvestigated." (PMID 36139097, 2022). "Taken together, our results indicate that expression of TIM-3 and CEACAM1 may represent a highly dysfunctional population of T cells, and we prove that their high expressions in tumor tissues predict poor prognosis of patients with HNSCC, especially for advanced ones." (PMID 34368221, 2021). "However, CEACAM1 may also have a tumor-suppressive function under some circumstances, since it was found that CEACAM1−/− mice developed a higher tumor burden than wild-type mice." (PMID 33868234, 2021). "In invasive tumor cells, there is a high proportion of the CEACAM1-short variant, which promotes migration, invasion and proliferation, functions which are not performed by CEACAM1-long." (PMID 34330892, 2021). "In this study, we revealed that CEACAM1 may be a suppressive factor in tumor cells." (PMID 31358815, 2019). "Therefore, the role of CEACAM1 in cancer cells may be different from its role of inhibiting anti-tumor immune responses in T cells." (PMID 31358815, 2019). "On the contrary, in early tumor stage pTa, CEACAM1 immunostaining became negative in tumoral cells, whereas the majority of blood vessels closely associated with or growing into the epithelial layer containing tumor cells were found CEACAM1-positive." (PMID 30406153, 2018). "CEACAM1 expression on tumor infiltrating T cells remained low whether or not the animals were treated with anti-PD-1 (muDX400) over multiple doses at levels that provided strong anti-tumor activity in vivo." (PMID 30349641, 2018). "Whether or not heterogeneity of a tumor or different mutations acquired by cancer cells in CRC patients can modulate CEACAM1’s effect on EPHA2 activity has yet to be investigated." (PMID 29262644, 2017). "Thus, CEACAM1 has the potential to be a novel tumor biomarker and warrants further study." (PMID 27074014, 2016). "The ITIM could presumably account for CEACAM1’s tumor suppressive properties." (PMID 24858421, 2014). "This may also explain the correlation of CEACAM1 expression on tumor cells and neutrophils density." (PMID 24587171, 2014). "Our research indicated that CEACAM1 may originate from tumour cells." (PMID 23885995, 2013). "Moreover, the change in serum CEACAM1 levels was more pronounced in early tumours than in advanced tumours, which may be of great clinical importance." (PMID 23885995, 2013). "PD-L1 and TIM3 ligands (LGALS9, PTDSS1, CEACAM1, and HMGB1) were identified on macrophages, DCs, and tumor cells." (PMID 40027748, 2025).
tumor (continued). "The interaction between its surface protein CbpF and the N-terminal domain of CEACAM1 primarily activates CEACAM1, inhibiting the IFN-γ secretion response of CD4+ T cells and supporting immune evasion within the tumor microenvironment." (PMID 41473772, 2025). "In the present study, we showed a trend toward increased expression of CEACAM-1 and CD155 on tumor cells after anti-PD-1 therapy in patients with unresectable advanced or recurrent G/GEJ cancer (p = 0.059 and p = 0.093, respectively)." (PMID 40801643, 2025). "Gal9, located on the tumor cell surface, binds to TIM-3, inducing TIM-3 oligomerization and complex formation with CEACAM1." (PMID 38785789, 2024). "The interaction between CEACAM1 and TIM-3 plays a crucial role in regulating autoimmunity and anti-tumor immunity." (PMID 38243323, 2024). "Significant correlations between CEACAM1 expression and BLBC stage (I-II vs III-IV), N-stage (N1-N2 vs N3-N4), and tumor status (tumor absence vs presence) (p = 0.001, 0.000, < 0.0001, respectively) were obtained by univariate cox regression analysis." (PMID 39513107, 2024). "In several cancers, CEACAM1 not only suppresses the inflammatory response and neoangiogenesis but also initiates extracellular matrix (ECM) remodeling during tumor development." (PMID 38715117, 2024). "Based on the previous study, the primary members CEACAM1 and CEACAM7 were recognized as tumor suppressors, while CEACAM5 and CEAMCAM6 were upregulated in almost 50% types of tumors and functioned as oncogenes." (PMID 36759883, 2023). "CEACAM1, CEACAM5, and CEACAM6 all have variable roles in tumor initiation, progression, and metastasis." (PMID 36741860, 2023). "Inhibition of CEACAM1 and TIM3 in CRC models synergistically stimulated the anti-tumor immune response." (PMID 38077351, 2023). "EBVaGCs also displayed a higher expression of anti-tumor immunity factors (PDL1, CD155, CEACAM1, galectin-9, and IDO1)." (PMID 36680216, 2023). "This is further supported by the increased expression of the anti-tumor immunity genes PDL1, CD155 (PVR), CEACAM1, LGALS9, and IDO1, all of which antagonize T cell responses via their interaction with inhibitory receptors." (PMID 36680216, 2023). "In a murine colorectal cancer model, co-blockade of CEACAM1 and TIM3 with monoclonal antibodies enhanced intrinsic anti-tumor responses, highlighting a potential target to enhance the efficacy of immunotherapies." (PMID 37143649, 2023). "HAVCR2 inhibits anti-tumor immunity by interacting with its ligand Galectin 9 (Gal9), phosphatidylserine (Ptdser) high mobility group box 1 (HMGB1), and carcinoembryonic antigen-related cell adhesion molecule 1 (CEACAM1)." (PMID 37005667, 2023). "Additionally, CEACAM1 can modulate the expression and activity of matrix metalloproteinases (MMPs) and enzymes involved in extracellular matrix degradation, which facilitates tumor invasion and metastasis by degrading matrix barriers and enhancing angiogenesis." (PMID 38067304, 2023). "Core genes (CEACAM1, CEP55, MELK) and were found to be involved in tumor, inflammation, necrosis, and proliferation." (PMID 37589542, 2023). "F. nucleatum has also been shown to interact with the immune inhibitory receptors TIGIT and CEACAM1, thus protecting CRC cells from cytotoxicity by NK cells and tumour-infiltrating lymphocytes." (PMID 35301576, 2022). "In our study, CEACAM1 and NDRG2 were protective factors for BC prognosis (HR < 1), which is consistent with the previous consensus that they are tumor suppressors." (PMID 36685904, 2022). "The IL-6 target genes MET, IGF1, MMP3, CEACAM1, MMP1 and WNT5A were upregulated, which enabled the tumour cells to become invasive." (PMID 35022523, 2022). "Killing of 19BBz against parent tumor cells and CEACAM1 overexpressing tumor cells was similar, but T3/28 CAR-T cells showed evidently higher killing against CEACAM1 overexpressing tumor cells at each ratio as compared with parent tumor cells." (PMID 34853180, 2021).
tumor (continued). "These clinical samples were then subjected to multiplex IHC staining to evaluate the expression levels of each inhibitory ligand (PD-L1, CEACAM-1, LSECtin, and MHC class II), cytotoxic T cell marker CD8 and tumor marker Cytokeratin." (PMID 33611641, 2021). "The result of flow cytometry showed that the tumor cell lines expressed low levels of TIM-3 ligands, including Gal-9, CEACAM1, and medium levels of PtdSer in vitro." (PMID 34853180, 2021). "Based on the results of TIM-3 staining, we continued to evaluate the expression of CEACAM1 on both HNSCC cells and tumor infiltrating lymphocytes to get a more comprehensive understanding of their roles in HNSCC progression." (PMID 34368221, 2021). "The results of WGCNA showed that the turquoise and blue modules, which are highly related to the eutopic endometrial cell group and the ectopic endometrial cell group, all contained tumor related genes, such as UBC, UBA52, RPS27A, PIK3CB, IRS1, and CEACAM1." (PMID 33868805, 2021). "Specifically, P5 displayed a two-fold decrease in CEACAM-1, while P1 showed a drop in CRISP-2 to undetectable levels following tumor resection." (PMID 33274048, 2020). "The other cluster including RASSF5, RASSF6, STAT1, CEACAM1, BNIP3L and SOCS2 is related to tumor suppression." (PMID 32201535, 2020). "As is shown in the multi-colour immunofluorescence staining analysis of 135 GC tissues, ~90% of tissues show that NECTIN2, CEACAM1, HMGB1, SIGLEC6 and CD15 were expressed in tumour cells, and CD44 was expressed in tumour cells in about 70% of tissues." (PMID 33311518, 2020). "NK CEACAM1 binds other CEACAM molecules present on nearby cells, including tumor cells; this interaction inhibits NKG2D-mediated tumor control." (PMID 32290478, 2020). "CEACAM1 is expressed at high levels on T cells activated by stimulation with IL-2 or anti-CD3 antibodies or activated NK cells, but also can be expressed on tumor cells and act in homophylic interactions with CEACAM1 on the immune cells." (PMID 31717326, 2019). "Carcinoembryonic antigen-related cell adhesion molecule 1 (CEACAM1) belongs to immunoglobulin superfamily, presents in various cells, and participates in cellular proliferation, apoptosis, angiogenesis, tumor metastasis, and pathogen recognition." (PMID 31072323, 2019). "Cell line screening showed the enrichment of cancer cells deprived of the expression of CD27, CEACAM1, CTLA4, LRIG1, PDCD1LG2, or TNFRSF18, suggesting their role as tumor suppressor." (PMID 31358815, 2019). "Among the genes, tumor related DAGLA and CEACAM1 were proven essential for the acquisition of resistance and for the recovery of sensitivity." (PMID 31847101, 2019). "Various studies indicate CEACAM1 to be a useful biomarker for pancreatic adenocarcinomas (PAC), being present in both tumor specimens and serum of patients compared to healthy individuals." (PMID 30406153, 2018). "In the present study, we sought to characterize expression profile of CEACAM1 and the effects of CC1 Ab in syngeneic mouse tumor models in vivo." (PMID 30349641, 2018). "Further studies are needed to investigate the prevalence and distribution of CEACAM‐1 on immune cells and other tumor cells, and the interaction between Tim‐3 and CEACAM‐1 in tumor development." (PMID 27516959, 2016). "CEACAM1 facilitates the maturation and surface expression of TIM-3 by forming a heterodimeric interaction, and the co-blockade of CEACAM1 and TIM-3 enhanced the anti-tumor immune response." (PMID 27283895, 2016). "These genes included tumor markers (MUC16), genes that control tumor migration (MYL9), metastasis (CEACAM6, VEGFC, CX3CL1, CST1, CCL5, S100A9, IGF1, NOTCH3), cell adhesion (FN1, CEACAM1), and inflammation (TRAF2, NF-κB2 and RelB)." (PMID 26090868, 2015). "In particular, human CEACAM1, CEA, and CEACAM6, which can be found on various epithelial cell types and derived carcinomas, are thought to shape the interaction between tumour cells and their stromal counterparts as well as immune cells." (PMID 24735478, 2014).